STMN1 (stathmin 1)
Diseases named in the same sentence as STMN1 in open-access papers (continued):
Sharing a sentence is not in itself a finding about the gene and the disease.
cancer (continued). "In view of FA patient’s hypersensitivity to chemotherapeutic agents and the occurrence of cancer types often associated with high STMN1 activity, anti-STMN1 therapy may provide an alternative cancer treatment option for FA patients." (PMID 26466335, 2015). "Because increased STMN1 activity or high expression of STMN1 is frequently associated with cancers, we propose that impaired phosphorylation of STMN1, which is associated with increased activity combined with DNA repair defects in FA cells, accounts for elevated cancer susceptibility in FA patients." (PMID 26466335, 2015). "STMN1 activities are regulated through phosphorylation-dephosphorylation mechanisms that control assembly of the mitotic spindle, and dysregulation of STMN1 phosphorylation is associated with mitotic aberrancies leading to chromosome instability and cancer progression." (PMID 26466335, 2015). "Notably, significant post-treatment upregulation of SELP+ high endothelial venules (HEVs) and APOD+ myofibroblastic cancer-associated fibroblasts (myCAFs), alongside a decline in STMN1+ capillary endothelial cells (cECs), is specific to the immunochemotherapy cohort." (PMID 40107247, 2025). "Thus, high STMN1 expression is associated with paclitaxel resistance and poor prognosis in cancers." (PMID 35186166, 2022). "One gene specifically expressed in Rep-MG is Stmn1, a mitotic gene, that has been shown to be involved in the proliferation and differentiation of cancer cells, indicating that the repopulated microglia from older mice were proliferative." (PMID 40777042, 2025). "ALA reduces the phosphorylation of ERK1/2 and its effectors, NIBAN2 and Stathmin 1, highlighting its potential as a therapeutic target in cancer treatment." (PMID 40868211, 2025). "This study analyzed the role of the phosphoprotein Stathmin 1 (STMN1) in regulating cancer cell growth and metastatic potential." (PMID 40723207, 2025). "Disrupting the ligand-receptor interaction (Ptn-Ncl), transcriptional regulation (Ybx1), or cytoskeletal dynamics (Stmn1) presents several avenues to reduce cancer cell motility, invasiveness, and metastasis." (PMID 39975141, 2025). "Analysing the concentrations of STMN-1 in the subgroups of patients with different degrees of cancer invasiveness, in relation to the control group, statistically significant differences were observed, K-W: H (2, N = 88) = 19.95; p = 0.0000." (PMID 40507426, 2025). "Since taxanes are commonly used to treat other hormonally dependent cancers, we also analyzed the link between STMN1, HGF, MET, and STMN1/MET gene expression signatures and taxane treatment response in an mBC patient cohort using the ROCplot dataset on BC." (PMID 40723207, 2025). "Other studies have interrogated the function of STMN1 phosphorylation at select serines in cancer cells other than PCa cells." (PMID 40723207, 2025). "In cell culture assays, the addition of a phosphate molecule to serine 16 on the Stathmin 1 protein increased cancer cell growth, while removing the phosphate inhibited cell growth." (PMID 40723207, 2025). "The analysis results showed that Macrophages_FABP4 exhibited significant depletion in cancer tissues, while Macrophages_SLENOP, Macrophages_SPP1, Macrophages-STMN1, and Macrophages_CXCL10 showed significant enrichment." (PMID 40916017, 2025). "In our study, four glycolysis genes (ENO1, STMN1, PKM, and CDK1) have been previously reported to be associated with cancer progression and drug resistance." (PMID 38840205, 2024). "Propofol at its IC30 did not influence the effect of paclitaxel on the expression of β‐tubulin but amplified the inhibitory effect of paclitaxel on stathmin 1 expression in cancer cells." (PMID 37162289, 2023). "Due to the mechanism of paclitaxel in cancer cells, stathmin 1 is a potential drug target of paclitaxel." (PMID 37162289, 2023).
cancer (continued). "We found that inhibiting miR-34a expression promoted STMN1 and inhibited β3-Tubulin, which decreased cancer cell death and increased apoptosis." (PMID 37165308, 2023). "Various studies have shown that the stathmin 1 protein plays a pivotal role in the evolution of cancer." (PMID 37162289, 2023). "Cell viability assay showed that the knockdown of STMN1 reduced the activity of cancer cells, and TUNEL staining showed a significant increase in apoptosis." (PMID 37165308, 2023). "Instead, STMN1 and the microtubule-associated kinase WNK1 are also involved in cell cycle control, cell survival and apoptosis, as components of diverse cancer signaling networks including PI3K/AKT, TNF and NF-κB signaling." (PMID 37305581, 2023). "Conversely, after knocking down STMN1, compared with the shNC group, the activity of cancer cells in the shSTMN1 + shNC group was significantly decreased, while the apoptosis of cancer cells was significantly increased." (PMID 37165308, 2023). "Up-regulation of STMN1 in cancer cells promotes cell proliferation, migration, metastasis and resistance to chemotherapy." (PMID 37305581, 2023). "In similar, we also found that the expression of canonical EMT-related genes was related to STMN1 expression in pan-cancer analysis." (PMID 35210426, 2022). "Since cancer metastasis involves complex processes, in which STMN1 has multiple metastasis-regulating targets, STMN1 is a potential target for cancer therapy." (PMID 36188577, 2022). "Stathmin1 (STMN1) has been proposed as a possible prognostic marker and a potential therapeutic target for some cancers." (PMID 37529254, 2022). "Studies have shown that DNA methylation of STMN1 has a potential relationship with cancer recurrence and prognosis." (PMID 36127700, 2022). "In contrast, the coefficients of SQSTM1, HSP90AA1, and STMN1 were positive, which was consistent with the reported function of promoting or suppressing cancer, indicating that DRGPI is a valuable prognostic biomarker for HCC patients." (PMID 35892599, 2022). "STMN1 has been shown to be involved in the development and progression of many malignant tumors, and the overexpression of STMN1 promotes their metastasis and growth, which is associated with poor prognosis." (PMID 35186166, 2022). "Tubulin (TUBB) is a druggable target as it has been ascribed a role in tumorigenesis and metastasis of many cancer entities and is critically regulated by Stathmin1 (STMN1)." (PMID 35063803, 2022). "Stathmin (STMN1), a microtubule destabilizing protein, has gained more attention in cancer pathogenesis in the past decade." (PMID 36188577, 2022). "To investigate STMN1’s potential role in cancer, we first searched for its expression in 33 human cancers." (PMID 36127700, 2022). "Oncoprotein STMN1 (also known as stathmin 1 and oncoprotein 18) plays a role in cell proliferation, motility, and cancer metastasis." (PMID 36139695, 2022). "Results of qPCR indicated that the STMN1 expression in HCC tissue were all significantly higher than those in the para-cancer tissue." (PMID 35210426, 2022). "STMN1 expression is now connected to a poor prognosis in a number of cancers, as well as cancer curability, recurrence, and resistance to adjunctive chemotherapy." (PMID 36127700, 2022). "Abnormally high expression of STMN1 is seen in many kinds of cancers, but the mechanisms of the dysregulated expression are inadequate." (PMID 33526768, 2021). "Collectively, these results demonstrated that STMN1 contributes to the FoxM1-induced proliferation and tumorigenesis of cancer cells in vitro and in vivo." (PMID 33526768, 2021). "As an oncogene in cancer cell biology, STMN1 functions in various cancers progression including cell proliferation, differentiation and cell cycle." (PMID 34253824, 2021). "To examine the oncogenic roles of STMN1 in vivo, we selected three cancer cell lines derived from LIHC, GC and CRC, respectively, to establish the xenograft model in nude mice." (PMID 33526768, 2021).
cancer (continued). "Our mechanistic study showed that FoxM1 transcriptionally activates STMN1 in cancer cells using the promoter reporter assay, ChIP-qPCR and bioinformatics analysis in ENCODE ChIP-seq database." (PMID 33526768, 2021). "Our work predicted several candidates as potential biomarkers for distinct stages of GE cancers, including previously identified CST1, INHBA, STMN1, whose expression correlated with cancer recurrence, or resistance to adjuvant therapies or surgery." (PMID 33828156, 2021). "Overexpression of STMN1 blocks the invasion of cancer cells and induces cancer cells growth arrest at the G2/M phase checkpoint." (PMID 34781983, 2021). "To investigate the effect of FoxM1 and STMN1 on cancer progression, we performed survival analysis of all solid tumors from TCGA database according to FoxM1 and STMN1 expression." (PMID 33526768, 2021). "The oncogenic mechanism of STMN1 overexpression is largely dependent on its ability to destabilize microtubules, leading to the promotion of cancer cell division, migration, and invasion." (PMID 33922244, 2021). "In this study, we used public database and tissue microarrays to analyze the expression pattern of FoxM1 and STMN1 and found a strong positive correlation between FoxM1 and STMN1 in multiple types of cancer." (PMID 33526768, 2021). "To investigate the expression pattern of FoxM1 and STMN1 in different types of cancers, we first analyzed the mRNA levels of FoxM1 and STMN1 in the Oncomine database." (PMID 33526768, 2021). "The results showed a significantly positive correlation between FoxM1 and STMN1 in all cancer samples derived from the TCGA database." (PMID 33526768, 2021). "To explore the mechanism by which FoxM1 regulates STMN1 expression, we performed RT-qPCR to test the mRNA levels of STMN1 in FoxM1-knockdown cancer cell lines." (PMID 33526768, 2021). "In cancers, STMN1 expression correlates with a malignant phenotypes and has been suggested as a therapeutic target." (PMID 33921319, 2021). "Taken together, we revealed a generally transcriptional regulation of FoxM1 on the expression of STMN1 in cancers." (PMID 33526768, 2021). "Based on our finding that STMN1 is transcriptionally regulated by FoxM1, we wondered to know the biological function of STMN1 in cancer cells." (PMID 33526768, 2021). "STMN1 has been reported to be upregulated across many kinds of cancers, and its high expression correlates with a poor prognosis." (PMID 33568625, 2021). "Our study, together with previous work, indicates that STMN1 is involved in complex regulatory networks and confers cell-type-specific regulation of cell function in different cancers." (PMID 33568625, 2021). "We used two independent shRNAs to stably knock down STMN1 and test the survival and proliferation in cancer cells." (PMID 33526768, 2021). "Cancer cells infected with STMN1-shRNA or pLKO.1-control lentivirus were subcutaneously injected into the BALB/c nude mice." (PMID 33526768, 2021). "To investigate the functional relationship between FoxM1 and STMN1 in cancers, we used Western blot to observe the expression pattern of FoxM1 and STMN1 in 18 cancer cell lines derived from LIHC, GC and CRC." (PMID 33526768, 2021). "And then using two independent short hairpin RNAs (shRNAs), we knocked down endogenous FoxM1 and STMN1, respectively, in three different types of cancer cell lines." (PMID 33526768, 2021). "In this study, cancer genomics data mining identified STMN1 as a prognosis biomarker and a therapeutic target for HCC." (PMID 33922244, 2021). "STMN1 (oncoprotein 18 and LAP18) has been suggested to be a potent predictive marker for a variety of cancers including LSCC." (PMID 32993587, 2020). "The data concerning correlation of the level of Stathmin-1 expression and resistance of cancer to chemotherapy are contradictory." (PMID 32823874, 2020).
cancer (continued). "Elevated levels of Stathmin-1 is a poor prognostic factor in many cancers, including leukemia, prostate, breast, lung, ovarian, cervical, endometrial, oral nasopharyngeal gastric, and colorectal cancers." (PMID 32823874, 2020). "The mechanisms by which STMN1 controls autophagy are not fully understood, but STMN1 positively regulates basal and rapamycin-induced autophagy in cancer cells." (PMID 31861937, 2019). "We further analyzed the differential expression of DPYSL4, HOMER1, ABCB6, CENPA, CDK1, STMN1 in cancer and adjacent tissues, and found that compared with adjacent tissues, the six genes in 309 HCC tissues were significantly up-regulated (P<0.01)." (PMID 31790363, 2019). "Although STMN1 is widely expressed and is an important negative regulator of tubulin, its functional role in cancer remains ill defined, especially with regards to anti-microtubule drug treatment efficacy." (PMID 30082792, 2018). "The work described herein provides a roadmap for studies on phosphorylation of STMN1 and microtubule-targeting anti-cancer agents." (PMID 30082792, 2018). "This study shows that hispidin induced necrotic cell death involving autophagy in SGC-7901 cancer cells by reversibly phosphorylating microtubule regulatory proteins, such as STMN1, disrupting microtubule homeostasis and inducing LMP." (PMID 28460485, 2017). "As a result of these studies, novel biomarkers for cancer diagnosis [e.g. stathmin 1 (STMN1), transgelin 2 (TAGLN2)] or potential targets for therapeutic intervention were proposed (e.g. phosphoglycerate mutase 1 (PGAM1))." (PMID 29050215, 2017). "Three of the autophagy targets of miR-101 (RAB5A, ATG4D and STMN1) have been validated in human cancer models." (PMID 29089869, 2017). "Stathmin (also known as Op18, p18, p19, stathmin 1 or metablastin), is upregulated in a variety of cancers and correlates with cell proliferation and migration of cancers, especially in malignant solid tumors." (PMID 27806343, 2016). "Multisite phosphorylation of STMN1 generates different combinations of STMN1 phosphoisomers that contribute to the overall regulation of cell invasion and cancer metastasis." (PMID 26087399, 2015). "Combining anti-STMN1 to chemotherapeutic drugs has been proven useful in blocking cancer growth in xenograft models." (PMID 26466335, 2015). "Collectively, these findings confirm that miR-221 plays a significant role in cancer development and progression by directly targeting STMN1." (PMID 25928257, 2015). "In support of our finding, depleting STMN1 in many cancer cell lines slows cell proliferation due to a delay in cell cycle progression during the G2 phase and ultimately leads to apoptosis." (PMID 25897432, 2015). "Depleting STMN1 in many cancer cell lines slows cell proliferation and ultimately leads to apoptosis." (PMID 25897432, 2015). "For example, stathmin 1 (STMN1) is up-regulated in several types of cancer and is correlated with disease progression and poor prognostic outcome." (PMID 25839165, 2015). "STMN1 was characterized as an important regulatory gene of microtubule dynamics, which were comprehensively studied in cancer." (PMID 24649266, 2013). "Cancer regulation by Stathmin 1 turned out to be the most significantly differentially affected pathway between NB and PCC." (PMID 23106811, 2012). "In fact recent studies point to Stathmin 1 as an important mitotic regulator highly expressed in many cancers that is under transcriptional control of E2F." (PMID 16987420, 2006). "The presence of STMN1 in these cells could reflect cytoskeletal remodeling and cell differentiation, key features of the transition to more aggressive and invasive cancer phenotypes." (PMID 39776361, 2025).
cancer (continued). "STMN1, as an important microtubule-regulating protein, participates in cell cycle regulation and anti-apoptotic processes through microtubule dynamics control, playing a key role in maintaining cancer stem cell properties." (PMID 40766320, 2025). "Taken together, STMN1, HGF, and MET overexpression are associated with cancer progression." (PMID 40723207, 2025). "Consistently, previous studies have also shown that depletion of STMN1 induces extensive microtubule stabilization and alters cytoskeletal organization in various cell types, including hematopoietic progenitor cells and cancer models." (PMID 41361792, 2025). "The interaction between pleiotrophin (Ptn), nucleolin (Ncl), Y-box binding protein 1 (Ybx1), and stathmin 1 (Stmn1) in cancer cells forms a complex signaling pathway that influences critical cellular processes, including proliferation, migration, and epithelial-mesenchymal transition (EMT)." (PMID 39975141, 2025). "Stathmin-1 is overexpressed in various cancers and is correlated with a poor prognosis." (PMID 39939315, 2025). "The relationship between STMN1 and cancer metastasis is controversial." (PMID 38385074, 2024). "Furthermore, CENP-A facilitates STMN1 (Stathmin 1) transcription by binding to its promoter while suppressing the ferroptosis of HCC cancer cells, allowing rapid growth of HCC and establishing a malignant phenotype." (PMID 39273649, 2024). "Furthermore, phosphorylated STMN1 contributes to the regulation of cell migration, cell invasion, and cancer metastasis." (PMID 39057719, 2024). "The upregulation of STMN1 implies heightened regulation of microtubule dynamics indicating increased cell cycle progression and cellular proliferation, a fundamental aspect of cancer development." (PMID 38524085, 2024). "Western blot results showed that inhibition of STMN1 expression could promote the expression of β3-Tubulin, which inhibited cancer cell proliferation and promoted cancer cell apoptosis." (PMID 37165308, 2023). "STMN1 acts both decreasing cancer invasion and promoting carcinogenesis." (PMID 37529254, 2022). "Upregulated genes in mEPCs, including IGF2, GPC3, S100A4, STMN1, and MDK, were semi-automatically assigned to the traditional cancer hallmark framework 15, including proliferative signaling, invasion/metastasis, genomic instability, immune response, and stem cell-like program." (PMID 36198671, 2022). "Furthermore, phosphorylated AKT and STAT were gradually reduced, suggesting that the oncogenic role of STMN1 in cancer metastasis was mediated by clusterin/AKT/MMP and STAT signaling." (PMID 36188577, 2022). "Almost all the FRGs in signaling pathways of pan-cancer, STMN1, RRM2, HELLS, FANCD2, and AURKA could significantly activate the cell cycle, but inhibit EMT, DNA damage response, hormones ER, RAS/MAPK, and RTK." (PMID 36349201, 2022). "Actually, literatures also reported that STMN1 could function as a secreted protein in serum and urine in various malignancies." (PMID 35210426, 2022). "Although it has been demonstrated that STMN1 silencing reduced invasion in PCa cell line as in many cancer types, this is the first study to demonstrate the effects on the autophagy, apoptosis, and invasion genes expressions of STMN1 silencing transfection in PC-3 cell lines." (PMID 37529254, 2022). "Due to the opposing mechanism, the overexpression of STMN1 resulted in the chemoresistance of paclitaxel in cancers, and knockdown of STMN1 could enhance the chemosensitivity of cancer cells." (PMID 35186166, 2022). "We found that the cell viability of the cancer cells significantly reduces with depletion of STMN1." (PMID 33526768, 2021). "A series studies have demonstrated the oncogenic role of STMN1 in various kinds of cancers." (PMID 33954109, 2021). "Increased expression of STMN1 benefitted anchorage-independent cancer cell growth by cJun." (PMID 34253824, 2021). "But the function of abnormally high level of STMN1 and its regulation mechanism in cancer cells remain unclear." (PMID 33526768, 2021).